MMP9 (matrix metallopeptidase 9)
Diseases named in the same sentence as MMP9 in open-access papers (continued):
Sharing a sentence is not in itself a finding about the gene and the disease.
hepatocellular carcinoma (continued). "This work showing that specific inhibition of MMP-9 expression by siRNA substantially suppresses the high invasive potential of HepG2 cells also suggests the decisive role of MMP-9 in basal hepatoma cell invasion." (PMID 21738655, 2011). "After patients were treated with chemotherapy, the DNA of hepatoma cells was damaged, and interferon regulatory factor 1 (IRF1) was activated, stimulating M2 macrophages to secrete a large amount of MMP9 in the form of exosomes to hydrolyze MICA on the surface of hepatoma cells." (PMID 40563539, 2025). "Previous studies have reported that Atractylodes lancea inhibited osteoarthritis by suppressing the expression and activity of MMP3, and Atractylodes lancea inhibited migration and invasion of hepatocellular carcinoma cells by decreasing the expression level of MMP9." (PMID 39177661, 2024). "Similarly, irradiation of hepatoma cells has been linked to the secretion of tumor necrosis factor-alpha (TNF-α), IL-6, VEGF, epidermal growth factor (EGF), MMP2, and MMP9, all of which enhance tumor invasion." (PMID 39759518, 2024). "The strong inhibitory effect of C-phycocyanin contained in Spirulina platensis protein extracts on the activity of human gelatinases MMP-2 (by 55.13%) and MMP-9 (by 57.9%) as well as the drop in the mRNA expression of both gelatinases has been documented in the hepatocellular cancer cell line HepG2." (PMID 39458962, 2024). "Moreover, MMP-9 has been suggested as a decisive contributor to promoting tumor growth and metastasis of hepatocellular carcinomas, mainly by promoting cell migration through the proteolytic degradation of the extracellular basement." (PMID 36432152, 2022). "Among them, MMP2 and MMP9 are involved in the metastasis of hepatocellular carcinoma." (PMID 35383533, 2022). "Additionally, MMP-9 rs3918242 was dramatically related to hepatocellular cancer (HCC) incidence among the overall populations in the recessive model (OR = 1.973, 95% CI = 1.068–3.645, p = 0.03)." (PMID 35574300, 2022). "In addition, TIPE2 inhibited invasiveness and tumor development via reducing MMP9 expression by targeting Rac1 in hepatocellular carcinoma (HCC) and gastrointestinal stromal tumor." (PMID 34249724, 2021). "In addition, EMP3 can promote hepatocellular carcinoma (HCC) by activating the PI3K/AKT pathway and uPA/MMP‐9 cascade, upregulation of which is closely associated with differentiation." (PMID 34268874, 2021). "Previous studies have shown that berberine could significantly inhibit the level of urokinase type plasminogen activator and MMP-9 in hepatoma cells, inhibit the degradation of tumor extracellular matrix, and thus inhibit tumor cells invasion and metastasis." (PMID 33407764, 2021). "During hepatoma progression, this biological process could be reversed by aberrantly low HBP1 expression, which promotes AFP effect on PTEN, MMP9 and caspase-3, thus induces proliferation and migration, and inhibits apoptosis in hepatoma cells." (PMID 33794968, 2021). "Up-regulation and activation of the receptor tyrosine kinase, Axl, in EMT-transformed hepatoma cells caused phosphorylation of Smad3 in its linker region, resulting in the induction of PAI-1, matrix metalloproteinase-9 (MMP-9), and Snail as well as TGF-β1 secretion in mesenchymal HCC cells." (PMID 33478130, 2021). "In addition, AIM showed inhibitory effects on the expression of MMP-2 and MMP-9 in MCF-7 cells, which is similar with the previous studies demonstrating the inhibitory effects of AIM on the expression of MMP-2 and MMP-9 in hepatocellular carcinoma cells." (PMID 32455624, 2020).
hepatocellular carcinoma (continued). "In a previous study, MMP-9 was up-regulated by SPOCK1 in a hepatocellular carcinoma cell line and treatment with an MMP-9 inhibitor significantly inhibited the invasion ability of SPOCK137, suggesting SPOCK1 may induce ECM remodeling through MMPs." (PMID 32555336, 2020). "Moreover, mRNA and protein levels of vimentin, N-cadherin, and MMP-9 were significantly increased in LINC01488 knockdown hepatoma cells, compared with cell lines transfected with control shRNA." (PMID 32575745, 2020). "NOTCH3 down-regulation by siRNA decreased the expression of MMP-9 in the hepatocellular carcinoma." (PMID 31811815, 2019). "KIF18A also promotes invasion and metastasis of hepatoma cells via MMP-7/MMP-9-related pathway." (PMID 30813560, 2019). "Similarly, depletion of Lysine-specific demethylase 1 (LSD1) and elevated expression of matrix metallopeptidase-9 (MMP-9) leads to an enhanced expression of LPAR6 in hepatocellular carcinoma." (PMID 29211777, 2017). "Furthermore, MMP-9 regulates migration of hepatocellular carcinoma cells in an ERK1/2-dependent mechanism." (PMID 29029486, 2017). "Although the anti-metastatic effect of vanillin by inhibiting MMP-9 expression in breast and hepatocellular carcinoma cells has recently been reported, the molecular mechanism by which vanillin attenuates migration and invasion in cancer cells is not fully demonstrated." (PMID 28257048, 2017). "The present results demonstrate that MFB has significant anti-invasion and anti-migration activities against SK-Hep-1 cells, a human hepatoma cell line, and that this effect is mainly associated with the induction of nm23-H1 expression and down-regulation of MMP-2 and MMP-9 activity." (PMID 27941649, 2016). "Additionally, HBX can increase the expression of CyclinD1 to promote cellular proliferation, and HBX-mediated migration of hepatoma cells is also related to MMP-9." (PMID 27821177, 2016). "In this study, we investigated the mechanisms underlying SNS-mediated inhibition of HBx-induced cell invasion and the inhibition of secreted and cytosolic MMP-9 production, using gelatin zymography and Western blot analysis in a human hepatoma cell line (HepG2)." (PMID 26446078, 2015). "On the other hand, drugs that target VEGF or MMP-9 directly might also be helpful for hepatoma treatment." (PMID 25334066, 2014). "VEGF and MMP-9 play important roles in hepatocellular carcinoma progression." (PMID 25334066, 2014). "Here we are going to determine whether GRP78 knockdown affect the ECM degradation and the role of MMP-2 and MMP-9 in these process in hepatocellular carcinoma cells." (PMID 22546345, 2012). "Therefore, we conclude that MMP-9 and u-PA are the most important proteases in metastasis of human hepatoma." (PMID 22363545, 2012). "Moreover, CAPE showed a strong inhibitory effect on the matrix metalloproteinase (MMP-9), which is related to the invasion and metastasis ability of hepatocellular carcinomas." (PMID 22458642, 2012). "MMP-9 has been described to be closely participated in capsular infiltration in hepatoma cells." (PMID 21738655, 2011). "Through the regulation of matrix metalloproteinases (MMP-2 and MMP-9) and the upregulation of E-cadherin expression, while downregulating N-cadherin and vimentin, RA also prevented the growth, invasion, and metastasis of hepatocellular carcinoma (HCC) cells in male BALB/c nude mice." (PMID 40427522, 2025). "Notably, MMP9 is the major MMP in the pathogenesis of EMT in hepatocellular carcinoma." (PMID 39544935, 2024). "By inhibiting MMP-9, vanillin may further limit the invasive and metastatic potential of cancer cells via the downregulation of the nuclear factor-B (NF-κB) signaling pathway in human hepatocellular carcinoma cells." (PMID 39451522, 2024). "once testified IFITM3’s promotion influences on hepatocellular carcinoma (HCC) invasion and metastasis by regulating MMP9 through p38/MAPK signaling." (PMID 37304304, 2023).
hepatocellular carcinoma (continued). "Finally, sinapine thiocyanate from SS significantly decreases the protein expression of PTGS1, PTGS2, Bcl-2, MMP-2 and MMP-9 and increases the protein expression of Bax to prohibit the proliferation, migration and invasion of hepatocellular carcinoma cells in SMMC-7721." (PMID 37124205, 2023). "Additionally, lycopene decreases the invasiveness of human hepatoma cells by reducing the attachment capacity of NF-κB and SP-1 (specificity protein) to DNA, thus allowing the down-regulation of the matrix metalloproteinase (MMP)-9 enzyme." (PMID 32718121, 2021). "Furthermore, previous studies demonstrated that the knockdown of BRD4 could decrease the expression level of MMP9 protein, thereby restraining the migratory and invasive abilities of squamous cell carcinoma and hepatocellular carcinoma." (PMID 31621555, 2020). "ATX-LPAR signaling axis is reported to induce MMP-9 expression in hepatocellular carcinoma (HCC) subsequently enhancing the invasive capacity of these cells." (PMID 33186124, 2020). "SNAIL can enhance the expression of mesenchymal genes, like vimentin in ovarian cancer and matrix degradation enzyme MMP9 in hepatocellular carcinoma (HCC)." (PMID 30781524, 2019). "Upregulation of MMP-9 has been observed in hepatocellular carcinoma (HCC) exposed to ionizing radiation, and radiation-induced HCC invasiveness is enhanced through the PI3K/AKT/NF-κB signal transduction pathway." (PMID 30359388, 2018). "Interestingly, MMP-9 is also able to cleave osteopontin into fragments with different biological activity, some of which particularly prone in the promotion of cell migration and invasion, as demonstrated in vitro for hepatocellular carcinoma cells." (PMID 28490808, 2017). "More importantly, EPM has the potential to promote hepatocellular carcinoma (HCC) invasion and metastasis by upregulating matrix metalloproteinase (MMP)-9 expression." (PMID 27362846, 2016). "The aim of the present study was to investigate the potential roles of the androgen receptor (AR) and matrix metalloproteinase (MMP)-2 and MMP-9 in hepatocellular carcinoma (HCC) tissues and whether their expression could be used as a predictor of the invasion and stage of cancer." (PMID 25667651, 2015). "The upregulation of MMP-9 is much higher in human hepatocellular carcinoma (HCC) SK-Hep-1 cells than HCC Huh-7 cells." (PMID 25566531, 2014). "Furthermore, after treatment with baicalein for 24 hours, there was a decrease in the levels of matrix metalloproteinase-2 (MMP-2), MMP-9 and urokinase-type plasminogen activator (u-PA) expression as well as proteinase activity in hepatocellular carcinoma MHCC97H cells." (PMID 24039823, 2013). "In vivo, co-culturing poorly invasive hepatoma cells with exosomes from highly invasive cells increased tumor volumes, upregulated lncRNA-PVT1, FoxM1, Ki67, and MMP9 expression, and downregulated miR-345-5p expression." (PMID 40486884, 2025). "In hepatocellular carcinoma (HCC), CAFs adjacent to tumors express MMP‐9 and TIMP‐1 in a spatially restricted manner, promoting ECM degradation at the invasion front while preserving structural integrity elsewhere." (PMID 40656546, 2025). "Activated CAFs further promote cancer progression by secreting angiogenic cytokines, including VEGF, MMP2, MMP9, b-FGF, and TGF-β, and enhance EMT progression in hepatoma cells." (PMID 38584703, 2024). "Another study reported that HSCs can mediate hepatoma progression by releasing factors that promote epithelial-mesenchymal trans-formation and angiogenesis, such as VEGF, MMP2, MMP9, bFGF, and TGF-β." (PMID 39742261, 2024). "Immunohistochemistry revealed that the expression of matrix metalloproteinase-9 (MMP-9) and vascular endothelial growth factor (VEGF) in hepatocellular carcinoma was lower in the TACE + GRGDSP nanoparticle group compared to the control group." (PMID 39679376, 2024).
hepatocellular carcinoma (continued). "Treatment of mouse skin fibroblast L929 cells and human hepatoma HepG2 cells with ASP extract significantly enhanced the protection against H2O2-induced oxidative damage and H2O2-induced MMP-9 mRNA expression, respectively." (PMID 39697544, 2024). "The administration of Polyphenon-B significantly reduced the incidence of DAB-induced hepatomas as evidenced by the modulation of MMP-2, MMP-9, tissue inhibitor of matrix metalloproteinase (TIMP)-2, and RECK as well as angiogenesis." (PMID 38139236, 2023). "In hepatocellular carcinoma cells, CTSB was shown to activate the phosphoinositide 3-kinase/Akt pathway, thereby promoting tumor invasion by increasing matrix metallopeptidase 9 expression." (PMID 37768200, 2023). "Notably, BARX1 expression is decreased in hepatocellular carcinoma (HCC), and its absence causes enhancement of tumour invasion and metastasis by inducing MGAT5 and MMP9 expression." (PMID 36927457, 2023). "In hepatoma cells, silencing KIF18A reduced the expression of cyclin B1, MMP-9, MMP-7, and Akt-related proteins and inhibited hepatoma cell growth, invasion, and metastasis." (PMID 37965453, 2023). "Previous studies have shown that quercetin inhibits cell migration and invasion in various cancer cell types, including breast, osteosarcoma, hepatoma, and oral cancer cells, by inhibiting the expression levels and activities of MMP-2 and MMP-9." (PMID 35337161, 2022). "In hepatocellular carcinoma (HCC) cell lines, the expression of MMP2 and MMP9 (enzymes that catalyze collagen hydrolysis) are upregulated after autophagy activation, which stimulates cell invasion." (PMID 35884904, 2022). "RA can inhibit the expression of Fyn in HepG2 hepatoma cells, as well as the proliferation, migration, and invasion of hepatoma cells, and the expression of matrix metalloproteinase-2 (MMP-2) and matrix metalloproteinase-9 (MMP-9) in a dose-dependent manner." (PMID 36278230, 2022). "In this study, MMP9, SPP1, HAGLR, LINC02202, and RP11-598F7.3 are considered as potential diagnostic biomarkers for hepatocellular carcinoma, and CD4+ memory resting T cells and CD8+ T cells are believed to be involved in HCC immune control." (PMID 35027925, 2022). "We extracted PNG using different extraction methods and compared their MMP-9 inhibitory effects using tumor necrosis factor (TNF)-α-treated rat cardiomyocytes (H9c2) and human hepatoma cells (HepG-2) as the bioassays." (PMID 36432152, 2022). "The inhibition of the STAT3 and MMP2/MMP9 signaling pathway reversed EMT and inhibited the migration and invasion of hepatocellular carcinoma cells." (PMID 34876128, 2021). "Bicuculline can effectively inhibit the migration and invasion of human hepatocellular carcinoma MHCC97-H cells which is related to the downregulation of VEGF, MMP-2, and MMP-9 gene expression and inhibition of JAK2/STAT3 signaling pathway activation." (PMID 34497656, 2021). "An alternative splicing event promotes extracellular cleavage of OPN by MMP-9, and the RGD-independent region of the cleaved fragment avidly enhances hepatocellular carcinoma (HCC) cellular invasion." (PMID 34440210, 2021). "In hepatoma cells, and colorectal cancer cells increased CTHRC1 activated expression of MMP-9, which is known to contribute to extracellular matrix breakdown and tumor promotion." (PMID 33717164, 2021). "Knockdown of TPX2 suppresses the invasion and proliferation of hepatocellular carcinoma cells via the deactivation of AKT signaling and suppression of MMP-2 and MMP-9 gene expression." (PMID 33531976, 2021).
hepatocellular carcinoma (continued). "In a human model of hepatocellular carcinoma, pterostilbene suppresses tumor growth by interfering in the signal transduction pathways of NF-κB and on the expression of VEGF, matrix metalloproteinase-9 (MMP-9), AP-1 and mitogen-activated protein kinase (MAPK)." (PMID 32085381, 2020). "In hepatocellular cancer, the transfection of the snake venom cystatin into tumoral cells has suppressed the tumor invasion and metastasis via suppressing MMP-2, MMP-9, and epithelial–mesenchymal transition." (PMID 33167431, 2020). "Quercetin (MOL000098) has been reported to inhibit metastatic potential of human hepatocellular carcinomas by decreasing p-Akt, MMP-2, and MMP-9." (PMID 33381039, 2020). "A doxycycline-treated group and a control group of engrafted human MHCC97H cells of hepatocellular carcinoma into BALB/c mice showed that doxycycline acted as an MMP-2 and MMP-9 inhibitor." (PMID 32377334, 2020). "In 2016, Tang Y found that 14-3-3β Promotes Migration and Invasion of Human Hepatocellular Carcinoma Cells by Modulating Expression of MMP2 and MMP9 through PI3K/Akt/NF-κB Pathway." (PMID 31737636, 2019). "MMP-9 can participate in capsular infiltration in hepatocellular carcinoma (HCC)." (PMID 31043859, 2019). "CLU increased MMP-2 expression in hepatocellular carcinoma cells, while CLU overexpression inhibited MMP-9 expression by reducing NF-κB activation in vascular smooth muscle cells." (PMID 31885575, 2019). "Fibrosarcoma and hepatocellular carcinoma cells expressed both MMP-2 and MMP-9, glioblastoma cells MMP-2 and PMA-induced MMP-9, and uterine leimyosarcoma cells only PMA-induced MMP-9." (PMID 27618095, 2016). "NDRG2 overexpression inhibits the expression of MMP2 and MMP9 in clear cell renal cell carcinoma (CCRCC) and hepatocellular carcinoma (HCC)." (PMID 26506239, 2016). "The present study showed that SNS effectively suppressed HBx-induced MMP-9 gene expression by suppressing the MAPK/AP-1 and PI3K/AKT/NF-κB cascades, with consequent suppression of tumor migration and invasion by human hepatoma HepG2 cells." (PMID 26446078, 2015). "We provide evidence that SNS exerts an anti-invasive and anti-migratory effect on HBx-activated hepatoma cells via the downregulation of PI3K/AKT, decreasing MAPK and IκB pathway signaling, NF-κB and AP-1 activity, and MMP-9 expression." (PMID 26446078, 2015). "Twist also enhanced hepatocellular carcinoma EMT and invasion through activating matrix metalloproteinase (MMP)-2 and MMP-9 expression." (PMID 25868853, 2015). "The expression of matrix metalloproteinase-9 (MMP-9) in BEL-7402 cells was downregulated and pulmonary metastases of hepatoma-22 in Kunming mice were curtailed." (PMID 26287217, 2015). "Knockdown of HOTAIR down-regulated proteins related to cell motility and metastasis, such as matrix metalloproteinase (MMP)-9 and vascular endothelial growth factor (VEGF), and decreased proliferation of Bel7402, a hepatoma cell line." (PMID 25334066, 2014). "Further investigation disclosed that the AP-1 activator TPA-induced MMP9 activity and the TPA-promoted migration and invasion of hepatoma cells were significantly attenuated by miR-101 but were enhanced by miR-101 inhibitor." (PMID 25260594, 2014). "The present study showed that Gen effectively suppressed TPA-induced MMP-9 gene expression by suppressing the MAPK/AP-1 and PI3K/AKT/NF-κB cascades, with consequent suppression of tumor migration and invasion of human hepatoma HepG2 cells." (PMID 24433534, 2014). "According to the expression levels of GRP78, MMP-2, MMP-9, MMP-14 and TIMP-1 in hepatocellular carcinoma cell lines SMMC7721 and hepG2, we used SMMC7721 as the in vitro invasion model for further functional analysis." (PMID 22546345, 2012). "Based on the expression status of GRP78, MMP-2, MMP-9, MMP-14 and TIMP-2 in hepatocellular carcinoma cell lines SMMC7721 and HepG2, we choose SMMC7721 to establish the in vitro invasion model for further research." (PMID 22546345, 2012).